UBQLN2 (ubiquilin 2)
Diseases named in the same sentence as UBQLN2 in open-access papers (continued):
Sharing a sentence is not in itself a finding about the gene and the disease.
Alzheimer disease (5 papers, 2013 to 2025). A progressive, neurodegenerative disease characterized by loss of function and death of nerve cells in several areas of the brain leading to loss of cognitive function such as memory and language. "Beyond α-syn, we showed that tau, whose fibrils characterize Alzheimer’s disease, partitioned into UBQLN2 droplets and aggregated during their maturation, an effect that was also suppressed by SO286." (PMID 41087580, 2025).
cognitive deficits (5 papers, 2016 to 2021). "Their model displayed cognitive deficits associated with UBQLN2 aggregates in hippocampus and evidence of neuronal death in cortex at the age of 130 days." (PMID 31319884, 2019). "Similarly, a rat model carrying the same mutation displayed cognitive deficits associated with UBQLN2 aggregates in hippocampus and evidence of neuronal death." (PMID 34830115, 2021). "Finally, we found that mutations in UBQLN2, which lead to neurodegeneration in humans, are defective in chaperone binding, impair aggregate clearance, and cause cognitive deficits in mice." (PMID 27477512, 2016). "The animals developed cognitive deficits, a dendritic spinopathy as well as UBQLN2 inclusions in the hippocampus." (PMID 31319884, 2019). "One mouse model expressing UBQLN2P497H under the control of hUBQLN2 promoter developed cognitive deficits, ubiquilin-2 inclusions in the hippocampus, and a dendritic spinopathy." (PMID 30377984, 2019). "Thus, UBQLN2 (mP520T) knockin mice develop cognitive deficits with age." (PMID 27477512, 2016). "Transgenic mouse models expressing hUBQLN2P497H manifested cognitive deficits, dendritic spinopathy, and UBQLN2 inclusions in the hippocampus, but neither TDP-43 pathology nor loss of motor neurons." (PMID 34830115, 2021).
Huntington disease (5 papers, 2014 to 2023). Huntington disease (HD) is a rare neurodegenerative disorder of the central nervous system characterized by unwanted choreatic movements, behavioral and psychiatric disturbances and dementia. "Ubiquitin, p62/SQSTM1, and ubiquilin 2 (UBQLN2) are components of intracellular inclusions in a number of neurodegenerative diseases, including Huntington disease and C9ORF72-associated ALS/FTD." (PMID 31665086, 2019). "Interestingly, Ataxin-10 (Atxn10) and Huntingtin-associated protein 1 (Hap1), proteins associated with the neurodegenerative disease spinocerebellar ataxia 10 (SCA10) and Huntington’s disease, respectively, were identified as UBQLN2 interactors." (PMID 27164932, 2016).
familial amyotrophic lateral sclerosis (4 papers, 2014 to 2022). An instance of amyotrophic lateral sclerosis that is caused by an inherited modification of the individual's genome. "Accumulation of Ubiquilin (Ubqn), the ubiquitin receptor whose human homolog ubiquilin 2 is associated with familial amyotrophic lateral sclerosis, also contributes to defects in postsynaptic growth and ubiquitin homeostasis." (PMID 28489002, 2017).
lung carcinoma (4 papers, 2023 to 2024). "It has been reported that the deregulation of UBQLN1 and/or UBQLN2 is associated with various neurological disorders; however, their cellular and biochemical role in various cell types including lung cancer remain largely unexplored." (PMID 37444499, 2023). "Previous studies from different groups have reported that UBQLN1 and UBQLN2 have been associated with various neurological disorders (Zeng); however, their cellular and biochemical roles in various cell types including lung cancer remain unexplored." (PMID 37444499, 2023). "However, loss of UBQLN2 led to an epithelial-to-mesenchymal transition (EMT)-like change in lung adenocarcinoma cells and promoted the invasion and metastasis of lung cancer, as was also demonstrated." (PMID 36644234, 2023). "Their previous studies reported that the loss of UBQLN proteins is associated with the progression of lung cancer, confirming that the low expression of UBQLN1 and UBQLN2 caused by miR-155 (as demonstrated by luciferase assays) promotes greater invasion and migration in lung cancer tumors." (PMID 38069307, 2023).
osteosarcoma (4 papers, 2020 to 2025). A usually aggressive malignant bone-forming mesenchymal neoplasm, predominantly affecting adolescents and young adults. "UBQLN2 had been identified as a risk factor for osteosarcoma and a novel marker for detecting urothelial cancer cells." (PMID 36644234, 2023). "In previous studies, Ubqln2 appeared to be a risk factor for osteosarcoma and a novel marker for detecting urothelial carcinoma cells in urine." (PMID 32293796, 2020). "Moreover, injection of UBQLN2 siRNA inhibited tumor growth in a rat osteosarcoma model." (PMID 39062505, 2024). "Meanwhile, higher expression levels of SMARCB1, UBQLN2, ENY2, and BAZ1B was observed in high-grade osteosarcoma prechemotherapy biopsy samples than that of MSCs." (PMID 40989695, 2025). "Under hypoxic conditions, knockdown of UBQLN2 leads to activation of JNK and p38, inducing apoptosis in the osteosarcoma cell line MG63." (PMID 39062505, 2024).
proteinopathy (4 papers, 2012 to 2016). "The findings from our mouse models are complimentary and together these models indicate that expression of ALS-linked ubiquilin-2 mutants cause progressive ubiquilin-2 pathology involving aggregate formation and proteinopathy." (PMID 26152284, 2015). "An increasing body of evidence indicates that TDP-43 proteinopathy underlies motor neuron degeneration caused by diverse genetic defects in various hereditary ALS, including ubiquilin 2, profilin-1, optineurin, valosin-containing protein (VCP), and C9ORF72." (PMID 23300771, 2012). "The role of ubiquilin 2 in proteolysis suggests that ubiquilin 2 pathology may be a general event in protein misfolding diseases." (PMID 24086754, 2013).
liposarcoma (3 papers, 2012 to 2023). A usually painless malignant tumor that arises from adipose tissue. "ALS models are commonly based on mutant superoxide dismutase 1 (SOD1), TAR DNA-binding protein 43 (TDP-43), fused in sarcoma or translocated in liposarcoma (FUS), the chromosome 9 open reading frame 72 (C9orf72) gene, ubiquilin 2 (UBQLN2), matrin 3 (MATR3), and senataxin (SETX)." (PMID 36672187, 2023).
motor neuron disease (3 papers, 2018 to 2025). "We next examined if the abrogation of UBQLN2 pathology found in the brain of double Tg mice extends to the spinal cord (SC), since expression of the mutant P497S transgene is associated with motor neuron disease." (PMID 33028421, 2020). "Mutations in the UBQLN2 gene have been linked to X-linked ALS and mice expressing ALS-linked mutant UBQLN2, but the normal protein displays disrupted proteostasis along with inclusions and motor neuron disease." (PMID 40180687, 2025).
Parkinson disease (3 papers, 2013 to 2025). A progressive degenerative disorder of the central nervous system characterized by loss of dopamine producing neurons in the substantia nigra and the presence of Lewy bodies in the substantia nigra and locus coeruleus. "A small molecule targeting UBQLN2 can suppress α-synuclein fibrillization, suggesting a potential strategy for treating Parkinson’s disease." (PMID 41087580, 2025). "Immunohistochemistry of brain sections from sporadic Parkinson’s disease patients revealed UBQLN2 in substantia nigra Lewy bodies, implicating UBQLN2 in α-syn aggregation in vivo." (PMID 41087580, 2025).
synucleinopathies (3 papers, 2013 to 2024). "In addition, ubiquilin 2 pathology was found in association with inclusion bodies in synucleinopathies and polyglutamine diseases as well." (PMID 24086754, 2013). "This knowledge of the role of UBQLN2 in regulating pS129 sheds light on one potential reason why UBQLN2 is found in Lewy bodies in synucleinopathies: to decrease pS129 levels." (PMID 36609661, 2023). "Outside of the colocalization of UBQLN2 with Lewy bodies in PD and DLB, little is known about the role of UBQLN2 in synucleinopathies." (PMID 36609661, 2023). "Previous studies showed ubiquilin immunoreactivity in cytoplasmic and nuclear inclusions in synucleinopathies and provided evidence that UBQLN2 dysregulation may contribute to α-synuclein-mediated toxicity." (PMID 38256197, 2024). "To determine whether UBQLN2 solubility is altered in synucleinopathies, we assessed soluble and insoluble levels of UBQLN2 in protein lysates from PD and DLB patient cingulate cortex." (PMID 36609661, 2023). "The protein quality control protein Ubiquilin-2 (UBQLN2) is known to accumulate in synucleinopathies, but whether it directly regulates α-synuclein is unknown." (PMID 36609661, 2023).
tauopathies (3 papers, 2013 to 2024). "Here, we studied whether ubiquilin 2 is associated with tau pathology using post-mortem material from tauopathy patients." (PMID 24086754, 2013). "No intracellular ubiquilin 2 positive inclusions were observed in hippocampal neurons in any of the tauopathy cases." (PMID 24086754, 2013). "We show that ubiquilin 2 positive inclusions are absent in these tauopathies." (PMID 24086754, 2013). "We found no ubiquilin 2 positive inclusions in AD and FTD-tau hippocampus and temporal cortex and conclude that ubiquilin 2 pathology as described for ALS does not occur in tauopathies." (PMID 24086754, 2013).
esophageal squamous cell carcinoma (2 papers, 2023 to 2024). Esophageal squamous cell carcinoma (ESCC) is a type of esophageal carcinoma (EC) that can affect any part of the esophagus, but is usually located in the upper or middle third. "Here, we explored the radiosensitizing effect of silencing UBQLN2 on esophageal squamous cell carcinoma (ESCC) and its mechanisms." (PMID 36644234, 2023). "For instance, the loss of UBQLN1 is associated with enhanced cell migration and induction of EMT, silencing UBQLN2 activates P38MAPK, enhancing the radiosensitivity of esophageal squamous cell carcinoma." (PMID 38969831, 2024).
hepatocellular carcinoma (2 papers, 2020 to 2023). A malignant tumor that arises from hepatocytes. "Overexpression of UBQLN2 in hepatocellular carcinoma patients indicates a poor prognosis." (PMID 36644234, 2023).
lung adenocarcinoma (2 papers, 2023). A carcinoma that arises from the lung and is characterized by the presence of malignant glandular epithelial cells. "Immunofluorescence staining of MYC revealed a drastic increase in nuclear expression of MYC following the loss of UBQLN1 and/or UBQLN2 in lung adenocarcinoma cells." (PMID 37444499, 2023). "We observed an increase in the expression of MYC following the loss of UBQLN1 or UBQLN2 in lung adenocarcinoma cell lines including A549, HOP62, H23, and H2009." (PMID 37444499, 2023). "The loss of UBQLN1 or UBQLN2 increases cell viability and clonogenic potential in lung adenocarcinoma cells H2030, H2009, and A549 cells." (PMID 37444499, 2023). "Next, we performed immunofluorescence staining of MYC in lung adenocarcinoma cell lines following a loss of UBQLN1 or UBQLN2." (PMID 37444499, 2023). "In the present study, we observed an increase in cell viability following the loss of UBQLN1 and UBQLN2 in lung adenocarcinoma cell lines, which was associated with a decrease in early apoptosis as revealed by annexin/7AAD staining." (PMID 37444499, 2023). "Next, to determine whether protein synthesis is responsible for increased MYC levels following the loss of UBQLN1 or UBQLN2, we treated lung adenocarcinoma cell lines with protein synthesis inhibitor cycloheximide." (PMID 37444499, 2023). "We observed an increase in cell viability and clonogenic potential following the loss of either UBQLN1 or UBQLN2 in lung adenocarcinoma cells, which we hypothesized was due, at least in part, to increased MYC expression." (PMID 37444499, 2023). "Interestingly, we observed the increased expression of cdk 2, 4, and 6 and cyclin D1, D3, and E1 following the loss of UBQLN1 and UBQLN2 in lung adenocarcinoma cells." (PMID 37444499, 2023). "In our study, involving lung adenocarcinoma cell lines, including A549 and HOP62, we observed that the loss of UBQLN1 and UBQLN2 increases cell migration." (PMID 37444499, 2023). "In the present study, we explored the effect of the knockdown of UBQLN1 and/or UBQLN2 on cell proliferation and clonogenic potential in lung adenocarcinoma cell lines." (PMID 37444499, 2023). "In our study using lung adenocarcinoma cell lines, we observed an increase in the expression of MYC following the loss of either UBQLN1 and/or UBQLN2." (PMID 37444499, 2023). "Since we observed an increase in cell proliferation following the loss of UBQLN1 and UBQLN2, we performed a clonogenic assay in lung adenocarcinoma cell lines following the loss of UQLN1 and UBQLN2." (PMID 37444499, 2023). "Using lung adenocarcinoma cell lines, we observed an increase in cell viability, clonogenic potential, and cell migration following the loss of either UBQLN1 or UBQLN2, which was associated with an increase in MYC expression." (PMID 37444499, 2023). "We performed a cell migration assay following a combined siRNA-mediated knockdown of either UBQLN1 or UBQLN2 with MYC in lung adenocarcinoma cell lines A549 and HOP62." (PMID 37444499, 2023). "Next, we were interested to see the effect of UBQLN1 and UBQLN2 knockdown on clonogenic potential and cell proliferation in lung adenocarcinoma cells." (PMID 37444499, 2023). "Immunofluorescence staining of MYC revealed a drastic increase in nuclear expression following the loss of UBQLN1 or UBQLN2, or a combined loss of both UBQLN1 and UBQLN2 in lung adenocarcinoma cells." (PMID 37444499, 2023). "Taken together, our results suggest for the first time a novel role of UBQLN1 and UBQLN2 in regulating MYC in lung adenocarcinoma cells." (PMID 37444499, 2023). "In the present study, we provided evidence that UBQLN1 and UBQLN2 regulate MYC stability in lung adenocarcinoma cells." (PMID 37444499, 2023). "Interestingly, using lung adenocarcinoma cell lines including A549, HOP62, and H23, we observed an increased expression of cdk2, 4, and 6 following the loss of either UBQLN1 or UBQLN2." (PMID 37444499, 2023).
lung adenocarcinoma (continued). "In conclusion, the present study provided evidence that UBQLN family members, especially UBQLN1 and UBQLN2, regulate MYC in lung adenocarcinoma cells." (PMID 37444499, 2023). "Interestingly, we observed an increase in the expression of oncogene MYC following the loss of UBQLN1 or UBQLN2, but not with UBQLN3 or UBQLN4 in lung adenocarcinoma cells." (PMID 37444499, 2023).
Angelman syndrome (1 paper, 2024). A neurogenetic disorder characterized by severe intellectual deficit and distinct facial dysmorphic features. "High levels of PEG10 have been implicated in the neurological diseases Angelman’s syndrome and ALS, where regulators of PEG10 abundance (UBE3A in Angelman’s, and UBQLN2 in ALS) are mutated and unable to control PEG10 levels." (PMID 39775359, 2024).
childhood cancer (1 paper, 2019). "We propose that PSMB6, PGGT1B, UBQLN2 and UQCR2 are housekeeping genes with low expression in childhood cancer." (PMID 31108950, 2019).
esophageal cancer (1 paper, 2023). A primary or metastatic malignant neoplasm involving the esophagus. "The results of IHC showed that UBQLN2 was mainly located in the cytoplasm of esophageal cancer cells and also weakly stained in the nucleus." (PMID 36644234, 2023).
lymph node metastasis (1 paper, 2023). "However, in the subgroup of ESCC patients with lymph node metastasis, the OS of patients with low expression of UBQLN2 was significantly better than that of patients with high expression of UBQLN2 (P < 0.01)." (PMID 36644234, 2023).
schizophrenia (1 paper, 2022). A major psychotic disorder characterized by abnormalities in the perception or expression of reality. "The UBQLN2 P500S and the TBK1 R271W/GRN T220I carriers have a family history of schizophrenia." (PMID 35964197, 2022). "The relevance between the UBQLN2, TBK1, and schizophrenia is unknown." (PMID 35964197, 2022).
neurodegenerative disease (27 papers, 2013 to 2026). A disorder of the central nervous system characterized by gradual and progressive loss of neural tissue and neurologic function. "UBQLN2 (Ubiquilin-2) is a shuttle factor which regulates protein degradation via the proteasome and autophagy, and is linked to neurodegenerative disease." (PMID 40663766, 2025). "Ultimately, continued research will enhance our understanding of neurodegenerative disease-associated UBQLN2 mutations, allowing for the development of new therapeutics." (PMID 40663766, 2025). "Of the five different UBQLN genes in humans, UBQLN2 is the most highly expressed in the nervous system and muscle tissue and has been linked to multiple neurodegenerative diseases." (PMID 40663766, 2025). "It should be noted, however, that Ubqln2−/− mice exhibit a comparatively mild form of neurodegenerative disease, suggesting that the gain-of-function due to mutation contributes significantly to the disease phenotype observed." (PMID 40663766, 2025). "Protein misfolding and oxidative stress are key pathogenic mechanisms in neurodegenerative diseases (ND), yet their connection in UBQLN2 ALS has been underexplored." (PMID 39769213, 2024). "The ubiquitin-adaptor protein UBQLN2 promotes degradation of several aggregate-prone proteins implicated in neurodegenerative diseases." (PMID 38472280, 2024). "Ubiquilin-2, a member of the ubiquilin protein family, plays a role in the regulation of various protein degradation pathways, and is mutated in some neurodegenerative diseases." (PMID 37359784, 2023). "Studies have established that UBQLN2 forms liquid-like condensates and accumulates in pathogenic aggregates, much like other proteins linked to neurodegenerative diseases." (PMID 33431932, 2021). "Mutations in the gene encoding ubiquitin chaperone Ubiquilin 2 (UBQLN2) have been associated with the early onset of neurodegenerative diseases, including ALS/FTD." (PMID 32867756, 2020). "Another ALS-linked gene, p62/SQSTM1, co-localizes with abnormal UBQLN2 inclusions, suggesting a synergistic effect of UBQLN2 and p62 during neurodegenerative disease progression." (PMID 30409191, 2018). "Stress granule (SG) formation and regulation are also affected by UBQLN2 mutations, and their dysregulation may contribute to the toxic protein aggregation and SG changes observed in neurodegenerative disease." (PMID 40663766, 2025). "Despite these advances, much remains unknown about the pathological role of UBQLN2 mutations in neurodegenerative diseases." (PMID 40663766, 2025). "UBQLN2 has been widely implicated in several neurodegenerative diseases, including PD." (PMID 41087580, 2025). "In a P506T UBQLN2 missense mutation model, neurotoxic amyloid-like aggregation was promoted over normal droplet dynamics, underscoring UBQLN2’s role in ubiquilin-dependent pathways for self-assembly and its potential ability to cause aggregation in neurodegenerative diseases." (PMID 39628898, 2024). "The molecular mechanism of neurodegenerative disease due to the UBQLN2 mutation remains unknown but could involve progressive accumulation of as-yet-unidentified Ubqln target proteins." (PMID 33277362, 2021). "In doing so, we have identified proteins whose abundance changes upon Ubqln2 perturbation and thus are not only linked to Ubqln2 function but could also potentially be involved in the development of neurodegenerative disease." (PMID 33277362, 2021). "With our introduction of a range of cellular and biochemical assays for UBQLN function, it should now be possible to examine these ideas with greater precision, including the prospect of determining why certain mutations in UBQLN2 cause neurodegenerative disease in humans." (PMID 27345149, 2016). "The mechanisms underlying UBQLN2-related neurodegenerative diseases remain unclear." (PMID 30409191, 2018). "Together, these suggest a more widespread phenomenon of UBQLN2 co-aggregation in neurodegenerative disease." (PMID 40663766, 2025).